AGTRAP (angiotensin II receptor associated protein)
Description:
Appears to be a negative regulator of type-1 angiotensin II receptor-mediated signaling by regulating receptor internalization as well as mechanism of receptor desensitization such as phosphorylation. Also induces a decrease in cell proliferation and angiotensin II-stimulated transcriptional activity.
Synonyms: ATRAP
Tractability: Antibody: UniProt predicts a signal peptide or a membrane-spanning region; its Gene Ontology location is reachable by antibodies, with medium confidence. PROTAC: its protein half-life has been measured.
Gene: Protein-coding gene on chromosome 1 (11,736,084 to 11,754,802, forward strand). Ensembl gene ENSG00000177674.
Subcellular location: Endoplasmic reticulum membrane; Golgi apparatus membrane; Cytoplasmic vesicle membrane
Subcellular location (Human Protein Atlas): Vesicles; Cytosol; Golgi apparatus
Pathways (Reactome):
Disease: Signaling by BRAF and RAF1 fusions
Gene Ontology:
Molecular function: protein binding; angiotensin type II receptor activity
Biological process: regulation of blood pressure; angiotensin-activated signaling pathway; response to hypoxia
Cellular component: Golgi apparatus; plasma membrane; cell cortex; cytoplasmic vesicle membrane; endoplasmic reticulum membrane; Golgi membrane
Genetic constraint (gnomAD): Loss-of-function variants: 8 observed, 17.22 expected, observed/expected ratio (o/e) 0.46, 90% interval 0.27 to 0.84. The upper end of that interval is the gene's LOEUF score, 0.84, which puts it in group 3 of 6, group 1 being the genes least tolerant of losing a copy. Missense variants: 187 observed, 219.14 expected, observed/expected ratio (o/e) 0.85, 90% interval 0.76 to 0.96. Synonymous variants: 74 observed, 91.64 expected, observed/expected ratio (o/e) 0.81, 90% interval 0.67 to 0.98.
Homologues: Orthologues: macaque AGTRAP (96% identical), chimpanzee AGTRAP (94% identical), rabbit AGTRAP (81% identical), mouse Agtrap (77% identical), guinea pig AGTRAP (77% identical), rat Agtrap (75% identical), zebrafish agtrap (57% identical), tropical clawed frog agtrap (55% identical), Drosophila melanogaster CG32638 (25% identical).